REN (renin)
Diseases named in the same sentence as REN in open-access papers (continued):
Sharing a sentence is not in itself a finding about the gene and the disease.
Obesity (continued). "TNF‐α, released by EAT in obesity, was also demonstrated to enhance adipocyte angiotensinogen protein expression and angiotensin II secretion, providing further evidence of the link between obesity and renin‐angiotensin‐aldosterone system activation." (PMID 38156451, 2024). "Obesity may impact blood pressure through various mechanisms, including leptin-mediated increased sympathetic activity and activation of the renin-angiotensin system." (PMID 38462604, 2024). "An increasing number of studies find obesity as a driver of chronic kidney disease progression, and the mechanisms are complex and include hemodynamic changes, inflammation, oxidative stress, and activation of the renin-angiotensin-aldosterone system." (PMID 38957660, 2024). "In obesity, the renin-angiotension-aldesterone system (RAAS) may be upregulated; plasma renin activity is increased, which regulates blood pressure and fluid balance." (PMID 39411599, 2024). "Additionally, obesity often activates the renin–angiotensin–aldosterone system (RAAS), resulting in heightened levels of renin and angiotensin." (PMID 39125283, 2024). "Furthermore, obesity’s influence on the renin–angiotensin–aldosterone system and the lipotoxic activity within the kidney underscores the complex interaction between obesity and renal health." (PMID 38540270, 2024). "Obesity can increase blood pressure through a series of mechanisms, including insulin resistance, activation of the sympathetic nervous system, and sodium retention resulting in increased renal reabsorption and activation of the renin-angiotensin system." (PMID 36895825, 2023). "EGF and renin in vascular health children with either obesity or type 1 diabetes." (PMID 36996194, 2023). "Increased activity of the adrenal renin-angiotensin system may be a potential mechanism for the relative hypoadiponectinemia seen in obesity." (PMID 36653874, 2023). "Taken as a whole, a picture emerges where excessive fructose and salt intake can contribute to the development of multiple determinants of metabolic syndrome, including insulin resistance, low grade inflammation, renin angiotensin aldosterone system activation, elevated serum uric acid, and obesity." (PMID 36901725, 2023). "Additionally, alterations in glomerular hemodynamics and over-activation of the renin-angiotensin-aldosterone system can prompt obesity-related nephropathy in some individuals." (PMID 37900143, 2023). "Fourth, patients with obesity may have lower plasma renin activity and systemic vascular resistance, and drug administration may play an important role in this result; adipose tissue releases hormones that have anti-inflammatory effects." (PMID 35590286, 2022). "It is hypothesized that adipocyte dysfunction in persons with obesity contributes to vascular and systemic insulin resistance and dysfunction of the sympathetic nervous system and the renin-angiotensin-aldosterone system." (PMID 35162176, 2022). "Furthermore, the renin–angiotensin–aldosterone system and renal sympathetic nervous system are activated in obesity, and these factors contribute to the pathogenesis of obesity-related sodium retention and glomerular hyperfiltration." (PMID 36319963, 2022). "Several possible explanations for the obesity paradox in HF have been raised, including the inverse relationship between NT-proBNP levels and BMI, attenuated response to the renin-angiotensin-aldosterone system, and increased muscle mass and muscular strength in those with high BMI." (PMID 35990945, 2022). "Studies have found overweight and obesity offer a better prognosis in chronic heart failure, possibly due to lower atrial naturetic peptide levels, lower sympathetic activation, and decreased reponse to activated renin-angiotensin-aldosterone system (RAAS)." (PMID 35313825, 2022). "A case in point is that obesity may increase in the activity of the sympathetic nervous system, alterations in renal function and the renin-angiotensin-aldosterone system." (PMID 36158841, 2022).
Obesity (continued). "Moreover, activation of the renin-angiotensin system serves as an important neurohumoral pathway of obesity contributing to the development of MetS." (PMID 36568079, 2022). "In the case of obesity, there is excessive secretion of pro-inflammatory and vasoactive adipokines such as angiotensinogen, angiotensin II, aldosterone, and resisting, along with an increase in plasma renin activity." (PMID 36293177, 2022). "This is consistent with the notion that leptin is a mediator in obesity-induced HT via neurogenic mechanisms and the activation of the renin-angiotensin system, and thus may indirectly promote cardiac hypertrophy, fibrosis and ventricular remodelling." (PMID 34679472, 2021). "Also, the renin-angiotensin-aldosterone system (RAAS) is activated as a result of obesity; this endocrine axis has considerable participation in the hemostasis of the cardiovascular system." (PMID 33809061, 2021). "Despite its impact in CKD and cardiovascular morbility and mortality, therapeutic strategies to fight against obesity-related CKD were limited for decades to renin-angiotensin blockade and bariatric surgery for patients who accomplished very restrictive criteria." (PMID 33928108, 2021). "Patients with or without CKD were comparable for factors that might potentially modify PAI‐1 expression, such as active cancer, metabolic syndrome, obesity, anticoagulant therapy, or renin–angiotensin system blockers." (PMID 34725920, 2021). "Packer postulated that obesity aggravates the deleterious interaction of leptin with the renin–angiotensin–aldosterone system and the renal sympathetic system leading to overactivity of neprilysin and, thus, deficiency in endogenous natriuretic peptides in these patients." (PMID 33723360, 2021). "Thus, seven of 12 proteins clustered around HDL-cholesterol, which, in turn, appeared to be mediating the effect of obesity; renin seemed to drive worse coronary atherosclerotic involvement in the presence of elevated HbA1c levels and reduced eGFR." (PMID 35187107, 2021). "Additionally, it has also been demonstrated that obesity and visceral adiposity has been positively correlated with the renin-angiotensin system that controls blood pressure." (PMID 33572921, 2021). "Obesity-related metabolic alterations such as inflammation and overactivation of the adipose renin–angiotensin system (RAS) may contribute to the progression of BC." (PMID 31963198, 2020). "The renin-angiotensin system in adipose tissue and its metabolic consequences during obesity." (PMID 32785498, 2020). "The mechanisms responsible for salt-sensitive hypertension in obesity and metabolic syndrome involve a multifaceted process that includes activation of the sympathetic nervous and renin-angiotensin systems, especially increased renal sympathetic nerve activity." (PMID 31315267, 2019). "In the renin-angiotensin–aldosterone system (RAS), high circulating levels of leptin and additional abnormalities have also been identified, explaining the association between obesity and hypertension." (PMID 31817392, 2019). "Obesity augments sympathetic nerve traffic due to hyperinsulinemia and renal norepinephrine spillover, which increase renal tubular reabsorption of sodium and as a consequence active the renin-angiotensin system (RAS)." (PMID 30011911, 2018). "Therefore, it is possible that obesity exerts its effect on PAI-1 and that PAI-1 subsequently participates in increasing blood pressure by associating with plasma renin activity and insulin resistance." (PMID 29636702, 2018). "Obesity can progressively raise blood pressure by altering cardiac output, cardiac systolic and diastolic function, renal pressure natriuresis and sympathetic nervous system and renin-angiotensin-aldosterone system activation." (PMID 29183297, 2017).
Obesity (continued). "Possible mechanisms may be related to obesity-induced haemodynamic changes, a higher glomerular filtration burden, hormonal effects, and the activation of the renin-angiotensin-aldosterone-system (RAAS)." (PMID 27484994, 2016). "RAAS activation in obesity has been attributed to increased synthesis of angiotensinogen by visceral fat, renal compression, and increased sympathetic outflows to the kidneys stimulating renin release." (PMID 27857694, 2016). "In established obesity several factors act in concert to maintain elevated sympathetic drive including hyperinsulinemia, obstructive sleep apnoea, baroreflex impairment, and activation of the renin-angiotensin system." (PMID 27857694, 2016). "NAFLD and CKD share common risk factors and probably liver and kidney damage may be the consequence of obesity-driven mechanisms of disease as lipotoxicity, oxidative stress, proinflammatory state, and renin-angiotensin axis activation." (PMID 27123461, 2016). "Together these data underscore the importance of digestive efficiency in the pathogenesis of obesity, and implicate dietary sodium, the renin-angiotensin system, and the AT2 receptor in the control of digestive efficiency regardless of mouse strain or macronutrient composition of the diet." (PMID 26068176, 2015). "Potential mechanisms by which obesity affects renal physiology include altered renal hemodynamics, insulin resistance, hyperlipidemia, inflammation, oxidative stress and activation of the renin angiotensin-aldosterone system." (PMID 25025298, 2014). "So, low levels of natriuretic peptide may activate the renin-angiotensin-aldosterone system, which may contribute to the development of obesity." (PMID 24506889, 2014). "While several mechanisms may be at play, this finding is most likely due in large part to the upregulation of the renin-angiotensin-aldosterone system (RAAS) in obesity, a proposed mechanism linking hypertension with obesity that is reversed by weight loss." (PMID 25018768, 2014). "We are currently studying the effect of high-fat diet on the two transgenic lines to test whether Pal3 is necessary for the upregulation of the renin expression in this model of obesity." (PMID 24288524, 2013). "Furthermore, none of these guidelines recommends choice of firstline and/or secondline antihypertensive agents based on phenotypical characteristics (race, age, obesity, and plasma renin activity)." (PMID 21566775, 2010). "Additionally, in obese patients, leptin may contribute to obesity-related glomerulopathy, potentially stimulating the renin–angiotensin–aldosterone system and exacerbating proteinuria and CKD." (PMID 40867871, 2025). "However, obesity may also have a complex effect on arterial stiffness in hypertensive patients by affecting the renin-angiotensin-aldosterone system (RAAS) and vascular endothelial function." (PMID 40568423, 2025). "In addition, changes in glomerular hemodynamics due to obesity may superactivate the renin–angiotensin–aldosterone system and lead to nephropathy, thereby diminishing uric acid excretion." (PMID 40565251, 2025). "Obesity may influence these three conditions through several interconnected mechanisms, including persistent inflammatory responses, oxidative damage, insulin resistance, and renin-angiotensin pathway stimulation." (PMID 41001669, 2025). "Similarly, obesity can activate the renin-angiotensin system, and alter adipokine and pro-inflammatory cytokine levels, causing hemodynamic changes, microvascular dysfunction, myocardial metabolic abnormalities, atherosclerosis, and calcification, all of which contribute to CVD." (PMID 40599621, 2025). "Obesity may not be a risk factor for long-term survival due to renin–angiotensin responses, cytokine and neuroendocrine profiles, and differences in the pathogenesis of cardiovascular disease in obese and non-obese patients." (PMID 36600190, 2023).
Obesity (continued). "Moreover, obesity-related increase in sympathetic tone counteracts the body's compensatory mechanisms for the abnormally elevated renin and aldosterone level that induce cardiac fibrosis and endothelial dysfunction and contribute to the development and complications of hypertensive heart disease." (PMID 37342440, 2023). "The United States among others have reported that young adults with obesity are more likely to require hospitalization and develop more severe disease than non‐obese young adults, consistent with the known increased distribution and activity of the renin–angiotensin system in obesity." (PMID 35029046, 2022). "Finally, the reduction of the initial obesity-associated hyperfiltration state to a normal or decreased GFR may also have played a role by decreasing sodium excretion and thus inhibiting renin secretion." (PMID 34675881, 2021). "In this regard, dysregulation of the natriuretic peptide (NP) system and inappropriate activation of the Renin–Angiotensin–Aldosterone System (RAAS) contribute to the development of obesity-associated DD in the absence of significant impairment in EF, a marker of systolic dysfunction." (PMID 33882908, 2021). "In addition, expression of renin-angiotensin system in adipose tissue is involved in the regulation of triglyceride accumulation, adipocyte formation, glucose metabolism, lipolysis, and the initiation of the adverse metabolic consequences of obesity." (PMID 32027667, 2020). "Additionally, some other mechanisms are known, including dysfunction in the renin-angiotensin-aldosterone system, increased tubular sodium reabsorption, and the effects of obesity-related hormones and cytokines such as leptin, adiponectin and Tumor Necrosis Factor-α." (PMID 27832768, 2016). "Many researchers have concluded the hyperuricemia is associated with the development of MetS, and the significant relationship between UA and MetS may be mediated by visceral fat accumulation and hypoadiponectinemia, or be a consequence of obesity and dysregulation of the renin-angiotensin system." (PMID 22719971, 2012). "Research has shown that obesity is a key driver of CKD progression, with mechanisms including hemodynamic changes, inflammation, oxidative stress, and activation of the renin-angiotensin-aldosterone system (RAAS)." (PMID 40110544, 2025). "A bidirectional link between renin-angiotensin-aldosterone system (RAAS) activity and obesity is well-established." (PMID 39148442, 2025). "Additionally, obesity-induced compression of the kidney may lead to increased sodium reabsorption and contribute to renal vasodilation, glomerular hyperfiltration, and increased renin secretion in obese subjects." (PMID 40422864, 2025). "Insulin, leptin, the renin-angiotensin-aldosterone system (RAAS), sodium excretion, and stress natriuresis were some of the mechanisms by which obesity raised blood pressure." (PMID 38887608, 2024). "The molecular pathophysiology of obesity-driven ECM remodelling or myocardial fibrosis is attributed to hypoxia, inflammation, activation of renin-angiotensin-aldosterone system, TGF-β signalling, and oxidative stress." (PMID 38908792, 2024). "Numerous studies showcase that the renin–angiotensin–aldosterone system is also activated in obesity, mainly because of the interaction with the SNS, which leads to the release of renin from the kidneys." (PMID 39457606, 2024). "In particular, this is through the impact of obesity and perirenal adipose tissue on renal SNS activity, with downstream effects on the renin–angiotensin–aldosterone system and sodium retention." (PMID 39062029, 2024). "Obesity results in the overactivation of the Sympathetic Nervous System (SNS) due to adipokine secretion, stimulation of the Renin–Angiotensin–Aldosterone System (RAAS), insulin resistance, baroreceptor dysfunction, and obstructive sleep apnea." (PMID 38297370, 2024).
Obesity (continued). "We then wanted to explore the impact of both dietary regimens on plasma aldosterone, renin and salt balance, given the strong implication of RAAS in the pathophysiology of both migraine and obesity." (PMID 37794395, 2023). "Another retrospective analysis of 275 adolescent and adult patients suggested that in non-primary aldosteronism, ARR predicted metabolic syndrome, obesity, and MAU, and was a better predictor than renin and aldosterone alone." (PMID 37848834, 2023). "Obesity activates RAS and increases RAS-related gene expressions in the adipose tissue, including Agt, Renin, Ace, and Agtr1." (PMID 37862361, 2023). "The adipocyte expression of mRNA of renin, ACE-1, and AT1R was higher in adipocytes derived from individuals with obesity." (PMID 36973648, 2023). "These pathways involve multiple key players, such as the renin-angiotensin-aldosterone system (RAAS), obesity, inflammation, oxidative stress and insulin resistance, which interact with each other and form a vicious cycle." (PMID 36589843, 2022). "Other pathways of obesity-related CKD involve alteration of adipokines, activation of Renin-Angiotensin-Aldosterone System (RAAS), and ectopic lipid accumulation within the kidneys." (PMID 35242044, 2021). "For example, as the members of the renin-angiotensin system (RAS), ACE2 and AGTR1 were reported to participate in the development and progression of obesity." (PMID 33255930, 2020). "This study showing elevated plasma renin, together with suppressed angiotensinogen and reduced levels of ACE2 protein suggests RAS overactivation in PCOS occurs in an obesity-independent manner." (PMID 32838280, 2020). "Male mice with global deletion of the renin gene are lean due to enhanced energy expenditure, have improved insulin sensitivity, and are resistant to development of HFD-induced obesity." (PMID 31262355, 2019). "Increasing BMI in humans is associated with increasing amounts of norepinephrine spill over in the kidneys, suggesting a link between obesity-related SNS activation and the neural release of renin." (PMID 28993801, 2017). "Previous studies demonstrated that the renin–angiotensin system (RAS), which is mainly mediated by the angiotensin II (Ang II) type-1 receptor (AT1R), plays an important role in obesity." (PMID 28335584, 2017). "Activation of tissue renin–angiotensin system (RAS), mainly mediated by an angiotensin II (Ang II) type 1 receptor (AT1R), plays an important role in the development of obesity-related metabolic disorders." (PMID 28335584, 2017). "Several investigations link an increased oxidative stress to the abnormal activation of the renin-angiotensin-aldosterone system (RAAS) and multiple conditions are able to activate RAAS, including obesity." (PMID 28582461, 2017). "Fourthly, obesity can induce abnormal kidney function, such as the increased glomerular filtration rate (GFR), primary sodium retention, and activation of the renin-angiotensin system (RAS), and so forth." (PMID 26247035, 2015). "In this respect, increased activation of renin-angiotensin system (RAS) and enhanced oxidative stress within cardiovascular tissue in obesity are important mediators of insulin resistance and vasoconstriction." (PMID 24966877, 2014). "Since the activity of the adipose-tissue renin–angiotensin system increases with higher adiposity, it was previously hypothesized that increased adipose-tissue renin–angiotensin system activity may represent a potential mechanism for the relative low-adiponectin levels seen in obesity." (PMID 25353014, 2014). "The present study compared RAS blockers, including a direct renin inhibitor, an ACE inhibitor and an AT1R antagonist, in a mice model of diet-induced obesity and insulin resistance." (PMID 23894285, 2013). "Animal models with systemic deletion of RAS components (Agt, renin, ACE, AT1a, and AT2) were protected from diet-induced obesity and metabolic disorders." (PMID 23483012, 2013).